INSL3 (insulin like 3)
Description:
Seems to play a role in testicular function. May be a trophic hormone with a role in testicular descent in fetal life. Is a ligand for LGR8 receptor.
Synonyms: Ley-I-L; RLF; RLNL; MGC119818; MGC119819
Tractability: Antibody: its Gene Ontology location is reachable by antibodies, with high confidence; UniProt places it where antibodies can reach, with medium confidence; UniProt predicts a signal peptide or a membrane-spanning region.
Gene: Protein-coding gene on chromosome 19 (17,816,512 to 17,821,574, reverse strand). Ensembl gene ENSG00000248099.
Subcellular location: Secreted
Pathways (Reactome):
Signal Transduction: G alpha (s) signalling events; Relaxin receptors
Gene Ontology:
Molecular function: G protein-coupled receptor binding; hormone activity; protease binding; protein binding; insulin receptor binding; signaling receptor binding
Biological process: G protein-coupled serotonin receptor signaling pathway; positive regulation of epithelial cell migration; positive regulation of wound healing; adenylate cyclase-inhibiting G protein-coupled receptor signaling pathway; cell-cell signaling; spermatogenesis
Cellular component: extracellular region
Genetic constraint (gnomAD): Loss-of-function variants: 8 observed, 6.55 expected, observed/expected ratio (o/e) 1.22, 90% interval 0.7 to 1.87. That is too few expected variants to judge how well the gene tolerates losing a copy. Missense variants: 178 observed, 167.74 expected, observed/expected ratio (o/e) 1.06, 90% interval 0.94 to 1.2. Synonymous variants: 86 observed, 75.57 expected, observed/expected ratio (o/e) 1.14, 90% interval 0.95 to 1.36.
Homologues: Orthologues: macaque INSL3 (95% identical), pig INSL3 (68% identical), mouse Insl3 (55% identical), guinea pig INSL3 (53% identical), zebrafish insl3 (27% identical).
Diseases named in the same sentence as INSL3 in open-access papers:
INSL3 is named in the same sentence as 70 diseases in open-access papers, as found by Europe PMC text mining. Sharing a sentence is not in itself a finding about the gene and the disease. The quoted sentences say what the papers report.
cryptorchidism (66 papers, 2007 to 2026). The failure of one or both testes of a male fetus to descend from the abdomen into the scrotum during the late part of pregnancy. "Another crucial marker for the activity and differentiation of LCs is INSL3, as depletion causes cryptorchidism in mice." (PMID 41476916, 2025). "To investigate the cause of inguinal cryptorchidism in INSL3-KI mice, we observed the gubernaculum and stained tissue sections from postnatal day 15 (P15) mice." (PMID 41219539, 2025). "Recently, mutation studies in human patients with bilateral cryptorchidism and male infertility reported bi-allelic loss-of-function (LoF) variants in INSL3 and RXFP2, while carriers of the heterozygous variant remain phenotypically unaffected." (PMID 40794697, 2025). "Mutations in the INSL3/RXFP2 genes are associated with cryptorchidism or undescended testis, a reproductive birth defect characterized by impaired fertility due to spermatogenic maturation arrest." (PMID 40794697, 2025). "Experimental studies have shown that cryptorchidism is associated with genetic abnormalities occurring in INSL3/RXFP2." (PMID 38407794, 2024). "A specific association of INSL3 gene polymorphism with cryptorchidism was incriminated in both animal and human studies." (PMID 37189986, 2023). "This literature review aims to discuss and analyze the importance of INSL3 and its mutation into cryptorchidism in both human and animal models." (PMID 37189986, 2023). "Loss of Insl3 causes cryptorchidism, or retention of the testes in the body cavity, which is associated with low serum testosterone and infertility, as well as a higher risk of developing testicular tumors." (PMID 35682797, 2022). "Another recent study reported two possible genetic biomarkers associated with canine cryptorchidism; hypomethylation of a single CpG site in the 5’-flanking region of INSL3, and a SNP in the 5’ flanking region of RXFP2." (PMID 35617214, 2022). "Loss of INSL3 or of its receptor RXFP2 results in cryptorchidism in mice, reflecting the importance of INSL3 for the proper testicular descent into the scrotum during the fetal life of most mammals." (PMID 33589679, 2021). "Last the higher levels of cord blood INSL3 in normal male newborns and the LH-dependent increase of INSL3 associated to spontaneous testicular descent in transient cryptorchidism, support a role for INSL3 during the inguino-scrotal phase." (PMID 30687232, 2018). "INSL3 is responsible for the first transabdominal phase of testicular descent and is thus directly implicated in cryptorchidism." (PMID 29740335, 2018). "If INSL3 and androgen are each indispensable for testicular descent, fetal Leydig cell function must play a central role in cryptorchidism susceptibility." (PMID 30083133, 2018). "In rodent experimental models, high doses of phthalates alter Leydig cell function affected INSL3 expression and androgen biosynthesis and caused cryptorchidism in rats." (PMID 26491444, 2015). "A complete loss of function of INSL3 or its receptor in mice or humans is associated with osteopenia/osteoporosis and cryptorchidism." (PMID 24478759, 2014). "The role of the INSL3 on testis descent was highlighted by the fact that mouse KO for the gene encoding Insl3 results in cryptorchidism." (PMID 23230429, 2012). "INSL3, expressed mainly in Leydig cells, mediates the first phase of testicular descent and mutation of this gene leads to cryptorchidism." (PMID 19664223, 2009). "Moreover, the abnormal expression of some proteins in the process of testicular descent is also one of the important causes of cryptorchidism, including INSL-3, NSE, SP, NFH, and DβH, which are closely related to the formation of cryptorchidism." (PMID 41217791, 2025). "The disruption of RXFP2 or INSL3 causes cryptorchidism and infertility." (PMID 39272405, 2024). "INSL3 gene polymorphism is considered a predisposing factor for cryptorchidism." (PMID 37189986, 2023).
cryptorchidism (continued). "Mutations in the INSL3 gene resulted in failure of testicular descent (cryptorchidism)." (PMID 36246983, 2022). "The celiac cryptorchidism is basically caused by mutations of INSL3 and receptor, while the inguinal cryptorchidism is mediated by androgen and may have nothing to do with INSL3." (PMID 35712443, 2022). "One of the INSL3 mutations was detected in a patient with bilateral cryptorchidism and micropenis." (PMID 37733393, 2022). "In addition, it has been shown that rat gubernacular cells show an increased production of cAMP upon stimulation with INSL3 and that bilateral cryptorchidism in INSL3- and RXFP2-deficient mice is linked with the impaired development of the gubernaculum." (PMID 35159259, 2022). "However, in vivo INSL3 together with testosterone promotes testicular descent, and reduced levels of INSL3 in cord blood at birth have been associated with cryptorchidism." (PMID 36266662, 2022). "Human cryptorchidism may be related to mutations in downstream signaling factors activated by INSL3 and its receptor." (PMID 34702182, 2021). "Cryptorchidism is usually induced by phthalates in rodent models and may be caused by reduction of testosterone and insulin-like 3 (INSL3) synthesis by fetal Leydig cells." (PMID 33912029, 2021). "The abnormal development of fetal Leydig cells could lead to the reduction of androgen and insulin-like 3, thus causing the male reproductive tract anomalies in male neonates, including cryptorchidism and hypospadias." (PMID 31780936, 2019). "Genetic experiments in mice show that ablation of the gene encoding either INSL3 or its unique cognate receptor RXFP2 leads to bilateral cryptorchidism, due to a failure of the gubernacular ligament to expand, and thereby promote the first transabdominal phase of testicular descent." (PMID 29740335, 2018). "Taken together, these data support the notion that cryptorchidism and/or hypospadias appear to be associated with a shift in the dynamics of INSL3 expression in the fetus, with precocious hormone expression and presumably Leydig cell differentiation in cases compared to controls." (PMID 29740335, 2018). "In utero exposure of rats to di(n-butyl) phthalate, a compound with antiandrogenic properties, caused reduced INSL3 expression in fetal Leydig cells and an increase in cryptorchidism, and INSL3 has been suggested as an endogenous marker of endocrine disruption." (PMID 26046833, 2016). "The interaction of Insl3 with Rxfp2 controls the differentiation of gubernaculum, the caudal genitoinguinal ligament critical for testicular descent, and deletion of Insl3 or Rxfp2 causes cryptorchidism." (PMID 17623071, 2007). "Moreover, INSL3 mutations are the same in all types of undescended testes." (PMID 37189986, 2023). "In addition, as fetal Leydig cells are a separate population from adult Leydig cells, it is possible that alterations in fetal Leydig function or INSL3 production or secretion may underlie the pathophysiology of cryptorchidism." (PMID 31611843, 2019). "The low INSL3 level at birth could be a cause or a consequence of cryptorchidism—it might suggest that the cause of cryptorchidism is low secretion of INSL3 or indicate that mild Leydig cell dysfunction can be identified already at the early life of the cryptorchid boys." (PMID 32010061, 2019). "Subtle Leydig cell dysfunction, characterized by increased variance in INSL3 levels and hence increased risk for susceptibility to other factors, and reduced testosterone/luteinizing hormone (T/LH) ratio, may occur in boys with cryptorchidism." (PMID 30083133, 2018). "Whilst a loss of INSL3 in the ovary appears to be linked to a reduction in antral follicle growth and maturation, no such gross aberration is evident for the adult testis, even when the receptor knockout is specifically targeted to the testis to avoid any repercussions caused by cryptorchidism." (PMID 24478759, 2014).
cryptorchidism (continued). "Lower levels of INSL3 have been found in the cord blood of male offspring with cryptorchidism compared to male offspring with normally descended testes." (PMID 40342221, 2026). "A Danish case–control study of 421 cases with cryptorchidism and 425 controls of singleton male offspring showed that the concentration of INSL3 in amniotic fluid samples during gestational weeks 13–16 was higher in cryptorchidism cases compared to controls." (PMID 40342221, 2026). "Mutations or polymorphisms in INSL3 and RXFP2 genes (encoding the INSL3 receptor) are associated with cryptorchidism." (PMID 41595460, 2025). "Our findings reveal how evolutionary changes in the INSL3/RXFP2 pathway contribute to natural cryptorchidism in mammals and provide insights for investigating reproductive health and cancer resistance in cryptorchid species." (PMID 41219539, 2025). "For example, in the mouse cryptorchidism model, the expression of testicular descent-related genes insulin-like peptide 3 (INSL3) and homeobox protein Hox-A10 (Hoxa10) was significantly reduced." (PMID 41217791, 2025). "The cetacean INSL3-KI mice we developed exhibited both bilateral cryptorchidism and male infertility, characterized by seminiferous tubule atrophy, progressive loss of germ cells, and an inability to produce mature sperm." (PMID 41219539, 2025). "This INSL3/RXFP2 pairing is essential for the proper descent of the testicles during development in mammals, and loss of rxfp2a results in cryptorchidism in mice." (PMID 40344089, 2025). "Overall, the phenotypes of cryptorchid males with mutations in the INSL3 and RXFP2 genes vary significantly from unilateral cryptorchidism in the first year of life to persistent bilateral cryptorchidism." (PMID 38407794, 2024). "In a separate study, cord blood INSL3 concentrations were significantly lower in boys with cryptorchidism than in controls, and in those who are persistently cryptorchid at 3 months, an increased LH to INSL3 ratio has been observed." (PMID 38436980, 2024). "Animal experiments indicated that dibutyl phthalate (DBP) disrupted rat testicular Leydig cell function and decreased the levels of T and INSL3, leading to increased incidence of cryptorchidism and hypospadias." (PMID 37409668, 2023). "The study outcome revealed that chronic fetal exposure to BPA leads to the disturbance of INSL3 pathway (INSL3 reduction levels, p = 0.01; R2 = 0.05) and the occurrence of cryptorchidism." (PMID 37886048, 2023). "In this literature review, we discuss and analyze the implication of INSL3 and the INSL3/LGR8 mutation in the occurrence of cryptorchidism in both human and animal models." (PMID 37189986, 2023). "The density of IGFR1 found on the cremasteric complex in cryptorchid patients was inferior than the value of the control group, thus proving the low stimulation of Leydig cells needed to produce INSL3." (PMID 37189986, 2023). "Apart from INSL3, the genitofemoral nerve and hormones (androgens) are involved in the physiopathology of cryptorchidism." (PMID 37189986, 2023). "There are many factors related to cryptorchidism, such as the INSL-3 and androgen both secreted by Leydig cells in the testicular interstitium." (PMID 35712443, 2022). "Several population studies, however, have indicated an association between heterozygous mutation in either INSL3 or RXFP2 and the incidence of cryptorchidism (usually unilateral)." (PMID 35464060, 2022). "These roles will not be discussed here, where the focus will be primarily on the role of INSL3 in the first phase of testis descent and cryptorchidism in the male fetus." (PMID 35464060, 2022). "Several reports indicate that exposure to other phthalates (DEHP and DBP) during pregnancy can down-regulate expression of Insl3 and induce cryptorchidism." (PMID 33912029, 2021).
cryptorchidism (continued). "INSL3 and its receptor relaxin family peptide receptor 2 (RXFP2) play important roles in descent of the testes during the transabdominal phase, and single-nucleotide polymorphisms in the INSL3 and RXFP2 genes are risk factors for cryptorchidism." (PMID 33256838, 2020). "INSL3 plays a key role in the fetal development and descent of the rodent testis, whereas mutations in genes encoding INSL3 and RXFP2 are rare causes of cryptorchidism in humans." (PMID 32982964, 2020). "Regarding BPA pre-natal effects, evidences are somewhat less represented than phthalates esters, but they seem related to alteration of steroidogenesis and INSL3 expression and, possibly, cryptorchidism." (PMID 32046352, 2020). "In addition to other estrogenic and anti-androgenic compounds, fetal testes cells exposed in culture to paracetamol and ketoconazole have decreased INSL3 levels which may be the mechanism by which analgesics, and possibly other endocrine disruptors, increase the risk of cryptorchidism." (PMID 31611843, 2019). "Both smokers and cases (cryptorchid/hypospadias) indicate a higher overall variance in INSL3 MoM, thus accounting for the failure to achieve significance in the absolute differences." (PMID 29740335, 2018). "This role is supported by the treatment of mice during mid-gestation with an INSL3 antagonist leading to cryptorchidism." (PMID 29740335, 2018). "In conclusion, our initial study showed that the association of INSL3 and ESR1 polymorphism with cryptorchidism in dogs seems to be unlikely." (PMID 30338045, 2018). "Recently, several studies have shown that INSL3 measured in cord blood, i.e., substantially later than its expression maximum in the fetus, is significantly reduced in cryptorchid cases compared to controls." (PMID 29740335, 2018). "With the aim of evaluating the pituitary–testicular axis in patients with cryptorchidism, serum levels of another Sertoli cell marker—inhibin B—and of Leydig cell markers—testosterone and INSL3—have also been assessed in different studies." (PMID 29922225, 2018). "Thirdly, they observed that individual INSL3 levels in cryptorchidic boys increased significantly when assessed at birth and at 3 months for both transient and persistent cryptorchidism." (PMID 30687232, 2018). "INSL3 was measured in amniotic fluid samples from 475 pregnancies (74% of cryptorchidism cases, 84% of hypospadias cases, and 71% of controls)." (PMID 26046833, 2016). "We aimed to study the associations between levels of amniotic fluid PFOS, fetal steroid hormone, and insulin-like factor 3 (INSL3) and the prevalence of cryptorchidism and hypospadias." (PMID 26046833, 2016). "In mice, deletion of INSL3 leads to bilateral intra-abdominal cryptorchidism in males due to defects in gubernacular differentiation, and reduced fertility in females due to disrupted estrous cycles." (PMID 21138583, 2010). "Studies in mice lacking RXFP2 had confirmed this receptor as INSL3’s sole mediator in vivo, with similar gene mutations identified in cryptorchid patients." (PMID 41219539, 2025). "In all experimental models, phthalates exposure, particularly di-2-ethylhexyl phthalate/dibutyl phthalate (DEHP/DBP), can reduce testosterone and INSL3 levels as well as AGD, and is associated with an elevated risk of cryptorchidism, with the risk being higher for mixtures of compounds." (PMID 41595460, 2025). "Disorders in INSL3 function, such as mutations in INSL3 or the RXFP2 receptor, may result in cryptorchidism." (PMID 39797156, 2024). "Even if the etiology of cryptorchidism in male boys is unknown, it is hypothesized that it is determined by multiple factors, and is most likely due to the altered signaling of INSL3/RXFP2." (PMID 37189986, 2023). "Prenatal exposure to oestrogens downregulated INSL3 expression and led to cryptorchidism in mice." (PMID 37409668, 2023).